SYT12 (synaptotagmin 12)
Description:
Synaptic vesicle phosphoprotein that enhances spontaneous neurotransmitter release but does not effect induced neurotransmitter release (By similarity). Unlike other synaptotagmins, it does not bind Ca(2+) or phospholipids (By similarity). Essential for mossy-fiber long-term potentiation in the hippocampus (By similarity).
Synonyms: SytXII; SRG1
Tractability: Antibody: UniProt predicts a signal peptide or a membrane-spanning region; its Gene Ontology location is reachable by antibodies, with medium confidence. PROTAC: ubiquitination databases record sites on it.
Gene: Protein-coding gene on chromosome 11 (67,006,772 to 67,050,870, forward strand). Ensembl gene ENSG00000173227.
Subcellular location: Cytoplasmic vesicle, secretory vesicle, synaptic vesicle membrane
Pathways (Reactome):
Neuronal System: Neurexins and neuroligins
Gene Ontology:
Molecular function: calcium ion sensor activity; calcium-dependent phospholipid binding; SNARE binding
Biological process: regulation of calcium ion-dependent exocytosis; vesicle-mediated transport; long-term synaptic potentiation; presynaptic modulation of chemical synaptic transmission; spontaneous exocytosis of neurotransmitter
Cellular component: exocytic vesicle; plasma membrane; hippocampal mossy fiber to CA3 synapse; presynapse; synaptic vesicle; synaptic vesicle membrane
Genetic constraint (gnomAD): Loss-of-function variants: 27 observed, 41 expected, observed/expected ratio (o/e) 0.66, 90% interval 0.48 to 0.91. The upper end of that interval is the gene's LOEUF score, 0.91, which puts it in group 3 of 6, group 1 being the genes least tolerant of losing a copy. Missense variants: 536 observed, 590.76 expected, observed/expected ratio (o/e) 0.91, 90% interval 0.84 to 0.97. Synonymous variants: 233 observed, 248.22 expected, observed/expected ratio (o/e) 0.94, 90% interval 0.84 to 1.05.
Homologues: Orthologues: chimpanzee SYT12 (99% identical), macaque SYT12 (97% identical), pig SYT12 (97% identical), guinea pig SYT12 (97% identical), rat Syt12 (96% identical), dog SYT12 (95% identical), mouse Syt12 (95% identical), rabbit SYT12 (83% identical), tropical clawed frog syt12 (69% identical), zebrafish syt12 (66% identical), Drosophila melanogaster Syt12 (34% identical), Caenorhabditis elegans snt-5 (23% identical). Paralogues in human: SYT6 (30% identical), SYT10 (29% identical), SYT9 (28% identical), SYT3 (27% identical), SYT5 (26% identical), SYT17 (26% identical), SYT2 (24% identical), SYT4 (24% identical), SYT1 (23% identical), SYT11 (23% identical), SYT8 (23% identical), SYT7 (23% identical), and 19 more.
Diseases named in the same sentence as SYT12 in open-access papers:
SYT12 is named in the same sentence as 19 diseases in open-access papers, as found by Europe PMC text mining. Sharing a sentence is not in itself a finding about the gene and the disease. The quoted sentences say what the papers report.
papillary thyroid cancer (3 papers, 2018 to 2021). "A recent study reported that SYT12 overexpression was correlated with metastasis and SYT12 was a biomarker that tended to predict greater disease progression in patients with papillary thyroid cancer." (PMID 31598163, 2019). "This study investigates three genes associated with thyroid tumors and shows that expression of one of them, synaptotagmin 12 (SYT12), tends to predict greater progression of disease in patients with papillary thyroid cancer." (PMID 29255621, 2018). "Of SYT family, SYT12 is detected as a biomarker of papillary thyroid cancer 10, but the molecular biologic function of SYT12 in other cancer cells and the interactions between SYT12 and cancer-associated signaling pathways remain unknown." (PMID 31598163, 2019). "SYT12 has some prognostic significance in papillary thyroid cancer." (PMID 29255621, 2018). "The expression of biomarkers (ITGA2, SYT12 and CDH3) was studied in a prospective cohort of patients with papillary thyroid cancer." (PMID 29255621, 2018).
Parkinson disease (3 papers, 2019 to 2022). A progressive degenerative disorder of the central nervous system characterized by loss of dopamine producing neurons in the substantia nigra and the presence of Lewy bodies in the substantia nigra and locus coeruleus. "Meanwhile, L-dopa (L-3,4-dihydroxyphenylalanine), which has been approved for Parkinson’s disease, could reduce cellular SYT12 expression, allowing cells to acquire a cellular phenotype similar to SYT12 knockdown." (PMID 36004367, 2022). "In addition, L-dopa, a drug for Parkinson's disease, controlled SYT12 expression, leading to similar phenotypes of SYT12 knockdown cells." (PMID 31598163, 2019). "Furthermore, treatment with L-3, 4-dihydroxyphenylalanine (L-dopa), a drug approved for Parkinson's disease, led to down-regulation of SYT12 and similar phenotypes to SYT12 knockdown cells." (PMID 31598163, 2019).
oral squamous cell carcinoma (2 papers, 2019 to 2023). "Synaptotagmin12 (SYT12) has been well characterized as the regulator of transmitter release in the nervous system, however the relevance and molecular mechanisms of SYT12 in oral squamous cell carcinoma (OSCC) are not understood." (PMID 31598163, 2019).
thyroid (2 papers, 2018 to 2021). "We found that SYT12 was significantly overexpressed in thyroid malignancy." (PMID 34659573, 2021). "However, many other molecular profiling studies have failed to implicate the ITGA2, SYT12 and CDH3 genes in thyroid tumorigenesis." (PMID 29255621, 2018).
thyroid cancer (2 papers, 2018 to 2021). "Next, we test the mRNA expression of SYT12 in different thyroid cancer cell lines, the result is also the same as collected surgical tissue samples and TCGA cohort." (PMID 34659573, 2021). "Next, we investigated the expression level of SYT12 and the relation between clinical information and SYT12 expression in thyroid cancer in the Cancer Genome Atlas (TCGA)." (PMID 34659573, 2021). "In brief, SYT12 is an oncogene that promotes thyroid carcinoma progression and metastasis in PTC." (PMID 34659573, 2021). "The SYT12 gene is usually over-expression in PTC, it was assumed that SYT12 plays a significant role in tumorigenesis and progression in thyroid cancer." (PMID 34659573, 2021). "Given that low TSH concentrations (presumably accompanied by high thyroid hormone levels) are beneficial for thyroid cancer outcomes, it could be speculated that the negative impact of SYT12 is not mediated through high thyroid hormone levels." (PMID 29255621, 2018).
thyroid tumor (2 papers, 2018 to 2021). A benign or malignant neoplasm affecting the thyroid gland. "But the part of the SYT12 gene taking in occurrence and development of thyroid tumor has yet remained unclear." (PMID 34659573, 2021). "In this study, we recruited a cohort of patients with PTC and determined the levels of ITGA2, SYT12 and CDH3 mRNA in resected thyroid tumors." (PMID 29255621, 2018).
amebiasis (1 paper, 2025). A parasitic infectious disorder caused by amoebas. "In this study, the differential genes EMCN and SYT12 have a fold change of ≥2.00 and Padj ≤ 0.05, and 2145 genes annotated to KEGG are significantly enriched in four pathways: the PI3K-Akt signaling pathway, focal adhesion, amebiasis, and the cancer pathway, in this order." (PMID 40428424, 2025).
cognitive decline (1 paper, 2023). "Analyses of human clinical testing and prototypic peptides show that higher levels of synaptic plasticity-related proteins, such SNAP25, SYT12, and VGF, and mitochondrial proteins, such as NDUFA, are associated with slower cognitive decline." (PMID 37338529, 2023).
pancreatic cancer (1 paper, 2020). "A total of 26 genes were found to be significantly associated with poor prognosis, while five of them, including SYT12, GJB5, RHOJ, GJB3 and IFI27, were of particular interest as they have not been previously associated with poor outcomes in pancreatic cancer cases." (PMID 32724299, 2020).
type 2 diabetes (1 paper, 2024). "PAX5, functioning as a classical transcription factor, can regulate the expression of many genes, such as MYC, WAPL, and several type 2 diabetes-related genes, including SFRP1 and SYT12." (PMID 38926764, 2024).
cancer (6 papers, 2019 to 2025). A tumor composed of atypical neoplastic, often pleomorphic cells that invade other tissues. "Although the SYT family primarily function as calcium ion receptors, SYT12 also plays a role in cancer cell proliferation, metastasis, and apoptosis." (PMID 40428424, 2025). "Of which, the top 20 differential expressed genes (DEGs) were mainly related to the progression of malignant tumors, including SYT12, CLDN10, COL9A3, SFRP1, MT1G, MTIH, etc.." (PMID 36253446, 2022). "To obtain the data to support the involvement of SYT12 in cancer progression, we performed PCR arrays in the shMock and shSYT12 cells." (PMID 31598163, 2019). "To investigate the status of the SYT12 expression as a cancer-related gene, we first conducted qRT-PCR and immunoblot analysis with 11 OSCC-derived cell lines and HNOKs." (PMID 31598163, 2019). "However, the molecular biologic role of SYT12 in cancer remains unknown." (PMID 31598163, 2019).
tumor (4 papers, 2019 to 2024). "In the clinical classifications, SYT12-positive OSCCs (IHC scores > median, 170.2) were associated significantly (P < 0.05) with tumor size, regional lymph node metastasis, and the TNM stage of the OSCCs." (PMID 31598163, 2019). "To make an investigation of the function of SYT12 in PTC, we initially detected the expression level of SYT12 in 40 pairs tumor samples and nearby normal thyroid tissue via RT-qPCR." (PMID 34659573, 2021). "Our analysis identified seven tumour suppressor genes (ITGA7, SLC45A1, TPPP, SCN4A, GIPR, SOGA3 and RAB6B) and six oncogenes (SAT1, SERPINE1, UPK2, SYT12, RASAL1 and CDH3) with significant false discovery rate (FDR)-adjusted P values (q-value) of less than 0.05." (PMID 38429478, 2024).
SYT12 also shares sentences with these, for which no sentence is quoted: oral cancer (2 papers); gynecologic cancer (1); laryngeal disease (1); lung adenocarcinoma (1); lymph node metastasis (1); Parkinsonism (1); schizophrenia (1).